DUS3L (dihydrouridine synthase 3 like)
Description:
Catalyzes the synthesis of dihydrouridine, a modified base, in various RNAs, such as tRNAs, mRNAs and some long non-coding RNAs (lncRNAs). Mainly modifies the uridine in position 47 (U47) in the D-loop of most cytoplasmic tRNAs. Also able to mediate the formation of dihydrouridine in some mRNAs, thereby regulating their translation.
Synonyms: DUS3; FLJ13896
Tractability: PROTAC: UniProt records ubiquitination sites on it; ubiquitination databases record sites on it; its protein half-life has been measured.
Gene: Protein-coding gene on chromosome 19 (5,784,832 to 5,791,225, reverse strand). Ensembl gene ENSG00000141994.
Subcellular location (Human Protein Atlas): Nucleoplasm; Cytosol
Gene Ontology:
Molecular function: mRNA dihydrouridine synthase activity; protein binding; RNA binding; tRNA-dihydrouridine47 synthase activity; tRNA dihydrouridine synthase activity; flavin adenine dinucleotide binding; metal ion binding
Biological process: regulation of translation; tRNA dihydrouridine synthesis; tRNA processing
Genetic constraint (gnomAD): Loss-of-function variants: 62 observed, 67.25 expected, observed/expected ratio (o/e) 0.92, 90% interval 0.75 to 1.14. The upper end of that interval is the gene's LOEUF score, 1.14, which puts it in group 4 of 6, group 1 being the genes least tolerant of losing a copy. Missense variants: 884 observed, 883.44 expected, observed/expected ratio (o/e) 1, 90% interval 0.95 to 1.06. Synonymous variants: 433 observed, 380.06 expected, observed/expected ratio (o/e) 1.14, 90% interval 1.05 to 1.23.
Homologues: Orthologues: chimpanzee DUS3L (99% identical), macaque DUS3L (96% identical), pig DUS3L (87% identical), dog DUS3L (86% identical), mouse Dus3l (81% identical), rat Dus3l (81% identical), guinea pig DUS3L (80% identical), tropical clawed frog dus3l (65% identical), zebrafish dus3l (61% identical), Caenorhabditis elegans Y37E11B.5 (43% identical), Drosophila melanogaster Dus3 (43% identical). Paralogues in human: DUS2 (15% identical), DUS1L (14% identical), DUS4L (11% identical).
Diseases named in the same sentence as DUS3L in open-access papers:
DUS3L is named in the same sentence as 2 diseases in open-access papers, as found by Europe PMC text mining. Sharing a sentence is not in itself a finding about the gene and the disease.
DUS3L shares sentences with these, for which no sentence is quoted: infection (1 paper); virus infection (1).